REST (RE1 silencing transcription factor)
Diseases named in the same sentence as REST in open-access papers (continued):
Sharing a sentence is not in itself a finding about the gene and the disease.
Huntington disease (40 papers, 2009 to 2025). Huntington disease (HD) is a rare neurodegenerative disorder of the central nervous system characterized by unwanted choreatic movements, behavioral and psychiatric disturbances and dementia. "An increasing body of data indicates that dysregulation of REST is implicated in neurodegenerative diseases, including Huntington’s disease and AD." (PMID 35456509, 2022). "In Huntington ́s disease models, mHtt further triggers a pathogenic cascade involving Sp1 activation, which leads to the upregulation of REST." (PMID 31361762, 2019). "A disruption of the interaction of NRSF/REST with its target genes has been reported to cause aberrant changes in neuronal gene expression in conditions such as epilepsy, Huntington’s disease, and Down’s syndrome." (PMID 31147527, 2019). "Overexpression of REST has been implicated in brain tumors, ischemic insults, epilepsy, and movement disorders such as Huntington’s disease." (PMID 30108242, 2018). "MiR-124a is another miRNA which targets BACE1 and has an additional role in excitotoxicity via regulating the glutamate transporter EAAT2 and is itself affected by the Huntington's disease associated transcription factor REST." (PMID 24133413, 2013). "For example, REST and its functions have been linked with Huntington’s disease, stroke, Down syndrome, and seizures." (PMID 21139978, 2010). "For example, Huntington's disease (HD) is caused by a polyglutamine expansion repeat in Huntingtin (Htt) and characterized, in part, by abnormal REST trafficking and transcriptional dysregulation." (PMID 19997604, 2009). "Impaired regulation of REST may result in ischemic responses and seizures as well as other major neurological disorders, evidenced by excessive nuclear localization in Huntington’s disease and its loss in Alzheimer’s." (PMID 40006989, 2025). "Additionally, REST is implicated to have a role in neurological disorders such as Huntington’s disease, Parkinsons, and also X-linked neurological retardation diseases such as SMCX." (PMID 40006989, 2025). "In addition, REST dysregulation has been implicated in several neurological diseases, including Huntington’s disease, Parkinson’s disease, and epilepsy." (PMID 38612548, 2024). "Interestingly, REST and Sirt1 are also implicated in the pathology of Huntington’s disease, with increased expression of Sirt1 found in Huntington’s disease-affected post-mortem brains." (PMID 33813634, 2021). "REST and REST-dependent epigenetic remodeling provide a central mechanism critical to the progressive neuronal degeneration associated with neurologic disorders and diseases including global ischemia, stroke, epilepsy, Alzheimer’s and Huntington’s disease." (PMID 33083114, 2020). "Restrictive element-1 silencing transcription factor (REST) is a key repressor of neuronal genes in stem cells and neuronal progenitor cells and its aberrant accumulation has been implicated in the pathophysiology of neurological disorders, such as Huntington's disease, epilepsy, and stroke." (PMID 41108075, 2025). "Huntington's disease (HD) is caused by a genetically mutated huntingtin (mHtt) protein with expanded polyQ stretch, which impairs cytosolic sequestration of the repressor element‐1 silencing transcription factor (REST), resulting in excessive nuclear REST and subsequent repression of neuronal genes." (PMID 28524599, 2017). "In addition, dysregulation of REST and its cofactors is implicated in the molecular pathophysiology of various diseases such as cardiac hypertrophy, ischemia, epilepsy, Down’s syndrome, Huntington’s disease, and X-linked mental retardation." (PMID 26690059, 2015). "HAR1A and HAR1B transcription was shown to be repressed by RE1-silencing transcription factor (REST) in Huntington’s disease." (PMID 39602392, 2024). "The abnormal expression of REST is involved not only in carcinogenesis but also in neurological diseases, such as Parkinson’s disease and Huntington’s disease." (PMID 38612548, 2024).
Huntington disease (continued). "In Huntington’s disease (HD), the increased binding of REST to RE1 reduced its target gene expression." (PMID 37892159, 2023). "In Huntington ́s disease, Htt indirectly regulates REST nuclear trafficking via the interaction of REST/NRSF-interacting LIM domain protein (RILP) and dynactin p150Glued*, an Htt-associated protein 1 (HAP1) bound to the Htt protein." (PMID 31361762, 2019). "Discovering mechanisms to reduce the cellular levels of mutant huntingtin and REST provide promising strategies for treating Huntington disease." (PMID 31361762, 2019). "In Huntington's disease, Htt regulates REST nuclear trafficking indirectly via the interaction of REST/NRSF-interacting LIM domain protein (RILP) with dynactin p150Glued*, an Htt-associated protein 1 (HAP1) that binds to the Htt protein." (PMID 31361762, 2019). "REST activation has also been reported in the brain of Huntington's disease patients and involves a cytoplasmic sequestering of REST by wild type huntingtin, which is lost with the mutant protein." (PMID 28286748, 2017). "The enrichment of genes involved in Huntington’s disease shed some light on the multifaceted nature of REST activity in human diseases." (PMID 27698411, 2016). "Studies have shown that REST is involved in psychiatric and neurological diseases, especially in AD, Huntington's disease and epilepsy." (PMID 26919115, 2016). "Dysregulation of REST activity is thought to play a role in diverse diseases including epilepsy, cancer, Down’s syndrome and Huntington’s disease." (PMID 26690059, 2015). "REST/NRSF-mediated deregulation is causative factor for several pathological conditions, such as Huntington's disease, cancer, ischemia, seizure activity, and neuropathic pain." (PMID 26413122, 2015). "An alternative mechanism of aberrant transcriptional regulation in Huntington's disease is increased nuclear localization of RE1-Silencing Transcription Factor (REST)." (PMID 24133413, 2013). "In healthy neurons REST is sequestered in the cytoplasm, but in Huntington's disease there is increased nuclear translocation of REST in neurons leading to increased gene repression, which has a negative effect on survival." (PMID 24133413, 2013). "Given that changes in the effective concentration of REST contribute to several pathologies—various cancers, Huntington's disease, cardiac hypertrophy, vascular smooth muscle proliferation—these SNPs should alter disease-susceptibility in carriers." (PMID 22496669, 2012). "For example, in Huntington's disease, excessive levels of REST are found in the nucleus, repressing target genes such as BDNF and resulting in neurodegeneration." (PMID 22496669, 2012). "The transcription factor REST, a silencer of neuronal gene expression, is also a target of miR-9 whose expression is downregulated in Huntington’s disease." (PMID 20806079, 2010). "Our data show that Hsp90 is necessary to maintain the levels of REST and mHtt, which suggests that the interactions between Hsp90-REST and Hsp90-Huntingtin could be potential therapeutic targets to Huntington ́s disease." (PMID 31361762, 2019). "Our data show that Hsp90 is necessary to maintain the levels of REST and mHtt, which suggests that the interactions between Hsp90-REST and Hsp90-Huntingtin could be potential therapeutic targets in Huntington's disease." (PMID 31361762, 2019). "Modulating the levels, transport o rate of synthesis and degradation of REST could be important for the possible treatment of Huntington ́s disease." (PMID 31361762, 2019). "Our data show that Hsp90 is necessary to maintain adequate levels of REST and mHtt, which suggests that the interaction between Hsp90-REST and Hsp90-Huntingtin could be a potential therapeutic target for treating Huntington's disease." (PMID 31361762, 2019).
Huntington disease (continued). "Indeed, REST seems dysregulated in the striatal tissue of Huntington’s disease (HD) patients and HD mouse models, where nuclear availability of REST in striatal neurons is modulated through its interaction with the huntingtin protein." (PMID 31165472, 2019). "The results of experiments in Huntington’s disease cell cultures transfected with a dominant-negative REST construct had already documented the importance of the elevated nuclear REST levels and the resulting increased repression of target genes in the diagnosis of the disease." (PMID 26465007, 2015). "The interest in such developments could involve not only Huntington’s disease but also other brain diseases in which changes in REST are critical for pathogenesis." (PMID 26465007, 2015). "Importantly, changes in the effective nuclear levels of REST are pathological in cancer, as well as cardiac hypertrophy, vascular smooth muscle proliferation, ischaemia and Huntington's disease." (PMID 22496669, 2012). "It is interesting to mention that in another neurodegenerative disorder, such as Huntington disease, it has been demonstrated that in NG108 cells overexpressing mutant Huntingtin (mHtt) Sp1 up-regulates REST by binding its promoter sequence." (PMID 34899171, 2021). "Huntington’s disease is associated with low levels of the REST target BDNF (brain derived neurotrophic factor), and restoration of BDNF can effectively reverse the Huntington’s disease phenotype, suggesting Sirt1 and REST may exacerbate the disease by downregulation of BDNF." (PMID 33813634, 2021). "It was interesting to note that genes involved in Huntington’s disease were enriched in this signature, namely MAP2K7, PDPK1, NCOR2, EP300, and REST." (PMID 27698411, 2016). "Recently it was found that repression of HAR1F by REST leads to its decreased expression in the striatum of Huntington’s disease, and that REST also interacts with DGCR5 and TUG1 lncRNAs leading to DiGeorge syndrome and Huntington’s disease." (PMID 22811697, 2012). "Although wild type huntingtin protein can interact with REST/NRSF and increase BDNF expression, mutant huntingtin, which has been found in Huntington’s disease patients, loses the ability to interact with REST/NRSF, resulting in repression of Bdnf and other REST/NRSF target genes." (PMID 34977362, 2021). "Previous studies reported that HAR1A could be repressed transcriptionally by REST, and HAR1 expression was lower in the striatum of Huntington’s disease patients than normal controls." (PMID 29108264, 2017). "Studies to profile miRNA expression in human tissue, mouse models of disease and cellular systems have revealed numerous expression changes in miRNAs not under REST control, suggesting that miRNA dysregulation is extensive in Huntington's disease." (PMID 24133413, 2013).
epilepsy (38 papers, 2014 to 2025). A brain disorder characterized by episodes of abnormally increased neuronal discharge resulting in transient episodes of sensory or motor neurological dysfunction, or psychic dysfunction. "cKO mice had higher susceptibility to kindling, suggesting a protective role of REST against epilepsy." (PMID 38034589, 2023). "As forebrain excitatory neurons are the common final pathway of seizure susceptibility, we investigated the role of REST in epilepsy by inducing REST conditional knockout (REST-cKO) specifically in excitatory neurons of the hippocampus." (PMID 38034589, 2023). "In the duplicated regions, we also considered the REST gene as another candidate disease-causing gene because of its potential to control fundamental transcription patterns that drive circuit excitability, seizures, and epilepsy." (PMID 34055682, 2021). "Alterations in REST expression have been associated with the onset of epilepsy; however, whether such alterations are deleterious or represent a protective homeostatic response remains elusive." (PMID 31998079, 2019). "Alterations of REST expression and/or activity have been associated with the onset of epilepsy, although the precise role of this factor in the progression of the pathology is still debated, and likely depends on the model employed and on the cell type analyzed." (PMID 31998079, 2019). "REST has also been mentioned as an augmenter of disease progression in the case of stroke and epilepsy, suggesting that REST cellular levels are critical." (PMID 40006989, 2025). "Accordingly, transient interference with REST/NRSF chromatin binding after an epilepsy-provoking SE suppressed spontaneous seizures for the 12 d duration of a prior study." (PMID 38641413, 2024). "The current experiments determined if transient interference with REST/NRSF chromatin binding prevented epileptogenesis enduringly or, alternatively, slowed epilepsy onset." (PMID 38641413, 2024). "Previously, blocking REST/NRSF function transiently in a developing brain prevented cognitive problems that accompany status epilepticus (SE)-induced epilepsy." (PMID 38641413, 2024). "Since the constitutive knockout of REST is embryonic lethal, the role of REST in epilepsy has been studied through conditional knockout (cKO) strategies." (PMID 38034589, 2023). "The first evidence that seizures can induce epigenetic changes in the brain comes from studies demonstrating the overexpression of REST after induction of epilepsy." (PMID 38034589, 2023). "On the other hand, previous research reported REST subcellular mislocalization and overexpression in epilepsy, leading to its abnormal function and the consequent channels and signalling proteins expression dysregulation." (PMID 37301955, 2023). "In clinical studies, it was found that REST and BDNF gene polymorphisms can be used as markers for the diagnosis of cognitive impairment in epilepsy." (PMID 36065764, 2022). "The mechanism of REST in epilepsy is complicated, and further research is needed to clarify the mechanisms of its dual effects." (PMID 36065764, 2022). "REST was shown to be overexpressed in the hippocampus in patients with drug‐resistant TLE, and the degree of epilepsy was positively correlated with the expression of REST." (PMID 36065764, 2022). "In another study, after specific REST KO in mouse forebrain excitatory neurons, the seizure onset threshold in mice with epilepsy was reduced, and mossy fibre sprouting was significantly increased." (PMID 36065764, 2022). "Such increases in REST represent the observations of epileptogenesis in humans, as REST mRNA and protein levels are overexpressed in epilepsy patients, with the level of REST protein correlating with the frequency of seizures." (PMID 33813634, 2021). "This review analyses data from different epilepsy models and discusses the contribution of REST to epileptogenesis." (PMID 33813634, 2021).
epilepsy (continued). "One gene of interest which is differentially regulated in epilepsy is the transcription factor Repressor Element 1-Silencing Transcription factor (REST)/Neuron Restrictive Silencer Factor (NRSF)." (PMID 33813634, 2021). "BDNF and its receptor TrkB are both upregulated in epilepsy and their repression by REST seems to be an important regulatory switch to protect against epileptogenesis." (PMID 33813634, 2021). "A precedent for such dynamic, selective regulation of a subset of target genes has been observed with targets of REST/NRSF that is induced after seizures, wherein only ∼10% of potential NRSF target genes were repressed in a pharmacological epilepsy model." (PMID 32536852, 2020). "The role of REST and its changes in the pathogenesis of diseases such as neurodegenerative diseases (Alzheimer’s, Parkinson’s, and Huntington’s diseases), epilepsy, and schizophrenia had already been discussed in our previous review." (PMID 31905747, 2019). "In a severe form of mouse epilepsy, the drug-resistant mesial temporal form, REST is overexpressed and the severity of the disease is proportional to its level." (PMID 31905747, 2019). "Overall, our data suggest that REST represents a potential target for therapeutic approaches addressed to pathologies characterized by network hyperexcitability, such as epilepsy." (PMID 31998079, 2019). "Epilepsy, the third most common disease of the human brain, is the one in which the role of REST has been investigated in the most detail." (PMID 26465007, 2015). "It has been reported that REST/NRSF dysregulation is implicated in some pathological disorders of the nervous system, such as global ischemia and epilepsy." (PMID 26413122, 2015). "In the literature of epilepsy, a few reports have emphasized the role of REST in the induction of the disease and possibly also in protection from it." (PMID 26465007, 2015). "The role of REST in epilepsy is controversial, and in the literature, opposite views coexist." (PMID 37892159, 2023). "Similarly, in a pentylenetetrazol (PTZ)-epilepsy model, mice bearing cKO of REST in all neurons displayed higher resistance to convulsions, higher PTZ lethal dose, increased survival, and alleviated epileptiform convulsions compared to control animals." (PMID 38034589, 2023). "The dual role of REST in epilepsy may be related to microRNA‐124, which effectively blocks the upregulation of REST and regulates REST target genes to exert an antiepileptic effect." (PMID 36065764, 2022). "In addition, increased expression of REST is neuroprotective in animal models of Parkinson’s disease, epilepsy, and fetal alcohol syndrome." (PMID 29084993, 2017). "REST is a repressor of neuron-specific genes in early fetal development whose activity is downregulated in mature neurons and dysregulated in a large array of brain pathologies including epilepsy." (PMID 27955713, 2016). "However, as discussed in detail in the Epilepsy section, the results induced in the neurons of REST knock-out animals are complex, involving the cooperation of numerous target genes." (PMID 26465007, 2015). "Indeed, it was recently shown that REST contributes to the homeostatic plasticity of inhibitory synapses, an effect that could be relevant in the context of epilepsy." (PMID 38034589, 2023). "However, the role of REST in epilepsy is currently controversial." (PMID 36065764, 2022). "In conclusion, the results of studies of the role of REST in epilepsy might appear contradictory." (PMID 26465007, 2015). "REST/NRSF is very likely a member of this SE-induced “orchestra,” because blocking its function prolonged latency to epilepsy and reduced overall seizure burden, in accord with recent work using selective deletion of the TF in hippocampal excitatory cells." (PMID 38641413, 2024). "The role of REST in the onset and development of epilepsy is still not clearly defined and the available experimental evidence provides contrasting results." (PMID 38034589, 2023).
epilepsy (continued). "This suggests the level of REST protein is not the only factor determining the role of REST in epilepsy." (PMID 33813634, 2021). "REST regulates many different genes which can individually contribute pro- or anti-excitatory effects, and the balance between all of these factors may determine whether or not an individual goes on to develop epilepsy following an initial brain insult." (PMID 33813634, 2021). "Not surprisingly, REST and CREBBP are both prominently present in the epilepsy PPI network generated here." (PMID 36982355, 2023).